PYY (peptide YY)
Diseases named in the same sentence as PYY in open-access papers (continued):
Sharing a sentence is not in itself a finding about the gene and the disease.
hypogonadism (4 papers, 2014 to 2024). A disorder characterized by decreased function of the gonads. "Adolescent girls with AN were at risk of low bone mineral density (BMD), which is associated with hypogonadism, low IGF-I, high cortisol and peptide YY (PYY) levels, and decreased lean mass." (PMID 24591772, 2014). "The impact of prolonged periods of hypogonadism and changes in serum cortisol, leptin, and peptide YY (PYY) may have on neurocognitive status, emotion, and mood is of particular concern." (PMID 38062345, 2024). "Another area of concern is the impact of prolonged hypogonadism and changes in hormones such as cortisol, leptin, and peptide YY (PYY) on neurocognitive status, emotion, and mood, thus posing additional challenges at an age when emotional lability is already common." (PMID 35937789, 2022). "Low BMD in AN is considered multifactorial and related to lower BMI, lower lean mass, hypogonadism, Growth Hormone resistance and low IGF-1, high cortisol levels, high PYY levels, and low levels of leptin, oxytocin, insulin and amylin." (PMID 37393263, 2023).
prediabetes (4 papers, 2019 to 2026). "Individuals with prediabetes or type 2 diabetes may instead depend more on dietary fiber intake to stimulate satiety and improve glycemic control, as well as other satiety hormones, such as CCK, GLP-1, and PYY, which are released mainly in response to fats and protein reaching the small intestine." (PMID 30861997, 2019). "There was also no statistical difference in fasting leptin or PYY between NGT and prediabetes phenotypes, nor was there an effect on post-prandial PYY iAUC responses during the OGTT." (PMID 41515274, 2026).
prostate carcinoma (4 papers, 2010 to 2024). A carcinoma that arises from epithelial cells of the prostate gland. "PYY or its fragments block tumor cell growth, migration, and invasion in breast, colorectal, esophageal, liver, pancreatic, and prostate cancer." (PMID 37373115, 2023). "PYY blocked the human PC3 prostate cancer cell line’s growth and increased VEGF production in these cells." (PMID 37373115, 2023). "PYY also blocked the growth of hepatic carcinoma/prostate cancer cells and decreased tumor volume/weight, and PYY3-36 inhibited the growth of esophageal cancer cell lines by inducing apoptosis." (PMID 37373115, 2023). "BMX contributes to the castration resistance in prostate cancer by positively mediating the activities of multiple receptor tyrosine kinases (RTK) through inducing the generation of phosphotyrosine-tyrosine (pYY) phosphorylation in their activation loop." (PMID 31130822, 2019). "For example, peptide YY (PYY), which belongs to the same family of peptides and acts through the same receptors as NPY, has been shown to inhibit proliferation of breast and prostate cancer cells via Y4Rs and pancreatic cancer cells via Y2Rs." (PMID 20508839, 2010).
acute myocardial infarction (3 papers, 2020 to 2023). Necrosis of the myocardium, as a result of interruption of the blood supply to the area. "In conclusion, we found PYY to be associated with various cardiovascular risk factors in patients with acute myocardial infarction." (PMID 33291235, 2020). "In this study, we investigated the association of serum PYY concentrations with parameters of cardiovascular risk and mortality in patients presenting with acute myocardial infarction." (PMID 33291235, 2020). "In this study, we found PYY levels to be associated with indicators of cardiovascular risk as well as cardiovascular events and all-cause mortality in patients with acute myocardial infarction." (PMID 33291235, 2020). "In this study, we aimed to investigate PYY serum concentrations in patients with acute myocardial infarction and to evaluate their association with cardiovascular events." (PMID 33291235, 2020). "Total PYY serum concentrations were assessed at time of hospital admission in patients presenting with acute myocardial infarction." (PMID 33291235, 2020). "Peptide YY (PYY), has been found to be associated with parameters of cardiovascular risk as well as cardiovascular events and mortality in patients presenting with acute myocardial infarction." (PMID 36720768, 2023). "This was mainly attributable to a significant association of PYY with nonfatal myocardial infarction (HR: 2.54; 95% CI: 1.12–5.76; p = 0.0259)." (PMID 33291235, 2020). "Material and Methods: PYY levels were assessed in 834 patients presenting with acute myocardial infarction (553 Non-ST-Elevation Myocardial Infarction (NSTEMI) and 281 ST-Elevation Myocardial Infarction (STEMI)) at the time of hospital admission." (PMID 33291235, 2020).
breast carcinoma (3 papers, 2019 to 2025). "In this prospective case-control study nested within the Mano a Mano Cohort Study, we assessed the risk of breast cancer with regard to plasma levels of c-peptide, gastric inhibitory polypeptide, insulin, leptin, monocyte chemoattractant protein-1, pancreatic polypeptide, and peptide YY." (PMID 31292496, 2019). "PYY treatment also demonstrates inhibitory effects on the proliferation of breast cancer." (PMID 40340969, 2025). "PYY also inhibited the growth of breast cancer cells (MCF-7) in vivo, and cAMP levels were reduced in these cells after treatment with PYY." (PMID 37373115, 2023).
COVID-19 (3 papers, 2020 to 2024). A disease caused by infection with severe acute respiratory syndrome coronavirus 2. "On the other hand, a decrease in GLP-1 (p < 0.05), leptin (p < 0.05), and PYY (p < 0.01) was reported in the colostrum of mothers suffering from COVID-19 compared with the control group." (PMID 38610889, 2024). "With regard to colostrum, adiponectin, resistin, and insulin concentrations showed an increase, while a decrease in GLP-1, leptin, and PYY was also reported in the colostrum of mothers suffering from COVID-19 compared with the control group." (PMID 38610889, 2024). "As for adiponectin, resistin, and insulin, their concentrations showed an increase; a decrease in GLP-1, leptin, and PYY was also reported in the colostrum of mothers suffering from COVID-19 compared with the control group." (PMID 38610889, 2024). "Patients who are overweight, obese, or have metabolic disorders tend to have different serum levels of adipokines and EB (cortisol, C-peptide, GLP-1, insulin, and PYY) compared to those without metabolic comorbidities, which could be associated with poor outcomes in patients with COVID-19." (PMID 39109758, 2024). "In addition, PYY increased the weight and size of the duodenum, ileum, and colon of adult mice; therefore, the reduction of this hormone, as recorded in the colostrum of mothers who suffered COVID-19, could have implications for the development of both the fetal and newborn gastrointestinal tract." (PMID 38610889, 2024).
eating disorder (3 papers, 2012 to 2023). A broad group of psychological disorders with abnormal eating behaviors leading to physiological effects from overeating or insufficient food intake. "This suggests strong influence of macronutrient type to postprandial secretion of PYY in patients with eating disorders." (PMID 22681985, 2012). "To understand whether PYY mediated the effects of medication and eating disorder features on gastrointestinal distress, we added PYY to the model along with medication, purging, binge eating, and their interaction." (PMID 37310328, 2023). "Different reactions of ghrelin and PYY to breakfast consumption among groups suggest that role of these hormones in regulation of energy homeostasis can be adjusted in dependence to acute status of eating disorder." (PMID 22681985, 2012). "The severity of eating disorder symptoms measured with the EAT-26 predicted fasting serum concentrations of NPY (p = 0.012) but not PYY." (PMID 33670342, 2021).
functional dyspepsia (3 papers, 2022 to 2025). "Furthermore, lower postprandial plasma PYY concentrations have been reported in patients with functional dyspepsia compared to healthy controls." (PMID 40142315, 2025). "Although postprandial PYY levels are reported to be reduced or unchanged compared to healthy control, there is a correlation between postprandial PYY levels and feelings of fullness, suggesting a potential role of this hormone in early satiety in functional dyspepsia." (PMID 35527812, 2022). "Studies have shown that stimulation of acupoint Zusanli(ST36) in rats could reduce the gastrointestinal hormone levels of ghrelin (GHRL), peptide YY(PYY), and glucagon-like peptide-1 (GLP-1), contributing to the amelioration of dyspepsia induced by cisplatin." (PMID 36304134, 2022).
osteoporosis (3 papers, 2019 to 2020). A condition of reduced bone mass, with decreased cortical thickness and a decrease in the number and size of the trabeculae of cancellous bone (but normal chemical composition), resulting in increased fracture incidence. "•Elevated PYY implicated in the pathogenesis of weight loss related osteoporosis." (PMID 31306808, 2019). "The aim of this review is to summarize the current knowledge of the actions of GIP, GLP-1, GLP-2, and PYY on bone metabolism, and to discuss future therapies targeting these receptors for the treatment of osteoporosis." (PMID 30863364, 2019). "Therefore, we proposed the hypothesis that Zhuang-Gu-Fang may interfere with the process of bone metabolism by regulating Leptin, Ghrelin, and PYY to prevent osteoporosis further." (PMID 33281915, 2020).
steatosis (3 papers, 2023 to 2025). Increased lipid within the cytoplasm of cells. "GPCR activation triggers the release of peptide YY (PYY) and glucagon-like peptide-1 (GLP-1), which delay gastric emptying, enhance satiety, and promote hepatic lipid oxidation, thereby reducing steatosis." (PMID 40362889, 2025).
type 1 diabetes (3 papers, 2013 to 2023). "The studies of PYY in animal models of human diabetes type 1 and patients with diabetesappear to yield contradictory results." (PMID 23292145, 2013). "Thus, whereas the number of PYY cells and theconcentration of PYY in the large intestine of NOD mice was low, the number of rectal PYYcells was high in patients with diabetes type 1." (PMID 23292145, 2013). "Notably, the hormones GAST and PYY have been reported to be expressed in the developing mouse pancreas and also in hPSC β-cell differentiation protocols, although they are absent from mature β-cells except in type 1 diabetes when GAST becomes upregulated." (PMID 32488111, 2020). "In animal models of human diabetes type 1, i.e. non-obese diabetic (NOD) mice, the numberof colonic PYY cells was reduced in diabetic, but not in pre-diabetic NOD mice." (PMID 23292145, 2013).
Abdominal obesity (2 papers, 2017 to 2023). Excessive fat around the stomach and abdomen. "We did not identify any rare variant in the PYY gene in young adults with abdominal obesity in our study." (PMID 37888112, 2023).
atherosclerosis (2 papers, 2021 to 2024). A disease characterized by the build-up of fatty material and calcium deposition in the arterial wall resulting in partial or complete occlusion of the arterial lumen. "SCFAs promote the release of the hormones peptide YY (PYY) and GLP-1, which lower blood pressure and inhibit atherosclerosis." (PMID 39502877, 2024). "SCFAs as signal molecules activate G-protein-coupled receptors mainly include GPR41 and Olfr78, which can promote the release of peptide YY (PYY) and glucagon-like peptide 1 (GLP-1), thus reduce blood pressure and inhibit the occurrence of atherosclerosis." (PMID 33816335, 2021).
carcinoid syndrome (2 papers, 2025). "Serum PYY, serotonin, and 24-h urinary 5-hydroxy indoleacetic acid (5-HIAA) were not measured in this case because carcinoid syndrome was not suspected clinically; this represents a retrospective limitation." (PMID 41244794, 2025).
celiac disease (2 papers, 2013 to 2015). An autoimmune genetic disorder with an unknown pattern of inheritance that primarily affects the digestive tract. "Basal and postprandial plasma levels of PYY are elevated inpatients with celiac disease." (PMID 23292145, 2013). "The changes in PYY could, however, befavorable in some gastrointestinal disorders such as celiac disease, systemic sclerosisand post-intestinal resection state." (PMID 23292145, 2013).
diarrheal disease (2 papers, 2013 to 2020). The condition of having at least three loose or liquid bowel movements each day. "Treatment of mutant mice with vehicle or with PYY significantly improved survival, consistent with therapeutic administration of supportive fluids in diarrheal disease." (PMID 32963229, 2020). "However, our results are consistent with previous work from our group in diarrheal disease as well as other studies demonstrating negative correlations between PYY and appetite." (PMID 23358528, 2013).
heart failure (2 papers, 2020 to 2022). Inability of the heart to pump blood at an adequate rate to meet tissue metabolic requirements. "In addition, PYY correlated with NT-proBNP as an indicator of heart failure, recapitulating earlier findings of elevated PYY levels in patients with advanced heart failure and cardiac cachexia." (PMID 33291235, 2020).
hypercortisolemia (2 papers, 2021 to 2022). "In particular, endocrine changes include hypothalamic amenorrhea, a nutritionally acquired growth hormone resistance with low insulin like growth factor-1 (IGF-1), relative hypercortisolemia, low leptin, insulin, amylin and oxytocin, and high peptide YY (PYY) and adiponectin." (PMID 35896857, 2022). "Also, several hormonal changes occur including somatotropin resistance with low insulin-like growth factor-1 (IGF-1) levels, hypothalamic hypogonadism, relative hypercortisolemia, and changes in appetite-regulating hormones including leptin, ghrelin, and peptide YY (PYY)." (PMID 35103128, 2021).
Nausea (2 papers, 2020 to 2025). A sensation of unease in the stomach together with an urge to vomit. "It is noteworthy that GIPR agonism can also attenuate PYY mediated nausea in preclinical models, suggesting optimism for either dual or triagonist analogues of PYY, GLP-1, and GIP." (PMID 39963285, 2025). "PYY infusion resulted in significantly higher self-reported nausea than vehicle infusion over the 8-hour study period peaking midinfusion." (PMID 31628465, 2020).
pancreatic cancer (2 papers, 2010 to 2023). "PYY decreased the growth of human Mia PaCa-2 and BxPC-3 pancreatic tumor cells and cAMP levels in Mia PaCa-2 cells." (PMID 37373115, 2023). "Moreover, the co-administration of PYY and vitamin E significantly increased the antitumor action against Mia PaCa-2 pancreatic tumor cells." (PMID 37373115, 2023). "Moreover, PYY and its fragments (e.g., PYY14-36) decreased the development of pancreatic tumor cells, and BIM-43004-1, a modified PYY22-36 Y2R synthetic agonist, also reduced the growth of these cells." (PMID 37373115, 2023). "The growth inhibition capacity of several PYY fragments (e.g., PYY1-36, PYY14-36, PYY22-36) has been studied; PYY14-36 showed the highest antitumor potency against PANC-1 and Mia PaCa-2 pancreatic cancer cells as well as the highest specific binding to tumor cells." (PMID 37373115, 2023). "On the contrary, PYY increased the growth of Capan-2 pancreatic tumor cells, whereas the peptide did not significantly increase the growth of Mia PaCa-2 pancreatic tumor cells." (PMID 37373115, 2023).
primary pulmonary hypertension (2 papers, 2006). "Recent work on patients with cardiac cachexia caused by severe pulmonary hypertension showed an exaggerated and early PYY response to a test meal when compared to control subjects." (PMID 16420657, 2006). "In non-critically ill patients with cardiac cachexia associated with primary pulmonary hypertension, an enhanced 'early' PYY response to an intragastric meal has been reported." (PMID 17173662, 2006). "Recent work by our group on patients with cardiac cachexia caused by severe pulmonary hypertension showed an exaggerated and early PYY response to a test meal when compared to control subjects." (PMID 16420657, 2006).
sarcopenia (2 papers, 2022 to 2024). Progressive decline in muscle mass due to aging which results in decreased functional capacity of muscles. "To ascertain the specificity of consistent GLP‐1 treatment in causing impaired myogenic differentiation, we used PYY as a control, given its stable levels in individuals with sarcopenia under starvation conditions." (PMID 38926763, 2024). "CCK, GLP-1, and PYY in our older people (mean age, 86.9 years) with sarcopenia had significantly higher serum levels in the three groups." (PMID 35565864, 2022). "We propose that anorexigenic gastrointestinal hormones, such as CCK, GLP-1, and PYY, might have important relationships with sarcopenia in the older people." (PMID 35565864, 2022). "We conclude that the older people in the sarcopenia group had significantly higher plasma concentrations of CCK, GLP-1, and PYY." (PMID 35565864, 2022). "We concluded that the older people with sarcopenia had significantly higher plasma concentrations of CCK, GLP-1, and PYY." (PMID 35565864, 2022). "The PYY concentration was significantly higher in the sarcopenia group than in the non-sarcopenia and pre-sarcopenia groups." (PMID 35565864, 2022). "In addition, we found older people with sarcopenia had significantly higher plasma concentrations of anorexigenic gastrointestinal hormones, including CCK, GLP-1, and PYY." (PMID 35565864, 2022). "The sarcopenia group had significantly higher fasting plasma concentrations of CCK, GLP-1, and PYY." (PMID 35565864, 2022).
schizophrenia (2 papers, 2022 to 2025). A major psychotic disorder characterized by abnormalities in the perception or expression of reality. "Lower PYY levels have been measured in the cerebrospinal fluid of patients with schizophrenia compared with controls, and it has been suggested that treatment with neuroleptics does not affect PYY levels, and low PYY levels could be used as a trait marker of the disease." (PMID 39941681, 2025).
acute coronary syndrome (1 paper, 2020). Signs and symptoms related to acute ischemia of the myocardium secondary to coronary artery disease. "Furthermore, PYY tertiles increased with increasing GRACE risk scores as an established risk calculator for patients with acute coronary syndrome." (PMID 33291235, 2020).
anemia (1 paper, 2014). A reduction in the number of red blood cells, the amount of hemoglobin, and/or the volume of packed red blood cells. "Moreover, SJDBT inhibited a production of IL-6, MCP-1, PYY, and GLP-1 and ameliorated cancer-induced anemia." (PMID 24963216, 2014).
autism spectrum disorder (1 paper, 2021). A spectrum of developmental disorders that includes autism, and Asperger syndrome. "Neuropeptide PYY has been associated with feeding patterns, and the comorbidity of autism spectrum disorders is alterations in feeding behavior." (PMID 33834688, 2021).
bacteremia (1 paper, 2022). "In conclusion, we used dual LPS exposure to mimic the first 36 h of bacteremia and showed elevated plasma concentrations of GLP‐1 and lowered plasma concentrations of PYY." (PMID 36117310, 2022).
brain astrocytoma (1 paper, 2012). A astrocytoma (excluding glioblastoma) that involves the brain. "This overlap was identified with a PYY cDNA isolated from a brain astrocytoma cDNA library that has an 80 nucleotide long exon located between regions A and B of the NAGS promoter." (PMID 22383952, 2012).
central precocious puberty (1 paper, 2025). "In this study, it was aimed to compare the circulating levels of ghrelin, leptin, PYY and NPY between the girls with idiopathic central precocious puberty (ICPP) and prepubertal girls, and also to evaluate the alterations in the levels of these hormones during leuprolide acetate treatment." (PMID 38896175, 2025). "In a recent study from Thailand, 18 girls with central precocious puberty were followed up under GnRH analogue treatment for 20 weeks, resulting in no change in serum ghrelin and PYY levels, but a significant increase in leptin levels along with fat percentage." (PMID 38896175, 2025).